IGFBP3 (insulin like growth factor binding protein 3)
Diseases named in the same sentence as IGFBP3 in open-access papers (continued):
Sharing a sentence is not in itself a finding about the gene and the disease.
-Deficient (2 papers, 2008 to 2019). "Leptin has been shown to regulate GH secretion and serum leptin levels have been associated with circulating IGF-1 and IGFBP-3 levels in normal and GH-deficient humans." (PMID 19017403, 2008).
acne (2 papers, 2024 to 2025). An inflammatory process of the sebaceous glands which is characterized by comedones, nodules, papules and/or pustules on the skin. "We defined the modulation of LL-37 and IGFBP-3 as primary outcomes due to their direct link to the pathophysiology of rosacea and acne, respectively, supplemented by secondary outcomes related to inflammatory cytokines and MMPs." (PMID 41614884, 2025). "Notably, the induction of IGFBP-3 points to the modulation of the IGF-1 pathway, offering a possible mechanistic basis for anti-acne benefits that extend beyond sebum reduction alone." (PMID 41614884, 2025). "While it does not replicate the full complexity of acne or rosacea, it allowed us to isolate and demonstrate CleodermTM’s ability to modulate central inflammatory pathways, such as the expression of LL-37 and IGFBP-3, which are relevant to these dermatoses." (PMID 41614884, 2025).
allergic asthma (2 papers, 2018 to 2026). A asthma with a basis in a pathological type I hypersensitivity reaction. "In an OVA-induced murine model of allergic asthma, IGFBP-3 expression was decreased, and levels of HIF-1α and HIF-2α in nuclear protein extracts from lung tissues were increased at 48 h after OVA inhalation compared to levels measured 48 h after saline inhalation." (PMID 30150897, 2018).
amyloidosis (2 papers, 2022 to 2025). A disorder characterized by the localized or diffuse accumulation of amyloid protein in various anatomic sites. "More importantly, we demonstrated that the knockdown of IGFBP3 efficiently suppressed APOE ε4-dependent AD pathologies during amyloid early-seeding stage in sporadic AD patient iNs, suggesting the role of IGFBP3 in APOE ε4-induced AD phenotypes." (PMID 36284363, 2022). "Knockdown of IGFBP3 was applied in the iNs to investigate the role of IGFBP3 in the APOE ε4-mediated amyloidosis." (PMID 36284363, 2022).
Barrett esophagus (2 papers, 2021 to 2023). Esophageal lesion lined with columnar metaplastic epithelium which is flat or villiform. "Calorie restriction reduced glycemia, IGF-1 and the IGF-1/IGFBP3 ratio, and improved insulin sensitivity in patients with Barrett’s esophagus (BE)." (PMID 37298551, 2023). "Data from our 24-month randomized trial on patients affected by Barrett’s esophagus suggest that a calorie and protein restriction program together with a specialized supervised approach can affect IGF-1 serum levels, reducing its secretion and also the IGF-1/IGFBP3 ratio." (PMID 34684639, 2021).
bladder urothelial carcinoma (2 papers, 2007 to 2020). "In addition, methylation levels of IGFBP3 have been associated with tumour recurrence in transitional cell carcinoma of the bladder." (PMID 17453001, 2007).
breast adenocarcinoma (2 papers, 2013 to 2019). "In order to address the role of TM219 in autophagy activation mediated by IGFBP3, we inactivated TM219 protein from the genome of Vero and human primary breast adenocarcinoma epithelial MCF7 cells using TM219 RNA guide-CRSPR/Cas9 to confirm the importance of TM219 protein in this process." (PMID 31220095, 2019).
breast disease (2 papers, 2007 to 2010). "Studies on genetic variants of IGF2 in relation to breast disease are few, and to our knowledge, the present study is the first to look at IGF2 polymorphisms in relation to levels of mammographic density, IGF1 and IGFBP3." (PMID 20302654, 2010).
cardiac hypertrophy (2 papers, 2023 to 2024).
chondrosarcoma (2 papers, 2016 to 2023). A malignant cartilaginous matrix-producing mesenchymal neoplasm arising from the bone and soft tissue. "In the previous study, IGFBP3 is regulated by GLI signaling in the progression to malignant chondrosarcoma." (PMID 37488121, 2023). "Heterogeneous expression of IGF1R, IR, IGF2R, IGF1, IGF2, IRS1 and IGFBP3 was seen, both at the mRNA and protein levels, in chondrosarcoma cell lines." (PMID 27418340, 2016). "IGFBP3 mRNA expression is detected in 8 out of 10 chondrosarcoma cell lines." (PMID 27418340, 2016).
COVID-19 (2 papers, 2022 to 2024). A disease caused by infection with severe acute respiratory syndrome coronavirus 2. "Expression levels of chorionic hormone synthesis genes such as CGB3 and EVT invasion- and differentiation-related genes such as IGFBP3 and EGFR in the second-trimester COVID-19 group were also consistent with those in the second-trimester control group." (PMID 38441496, 2024). "We observed that RBM15B, HNRNPA2B1, and VIRMA may be protective factors in the development of COVID-19, and the opposite performance was found in ELAVL1, RBM15, FMR1, IGFBP3, and METTL3." (PMID 35655464, 2022).
endotoxemia (2 papers, 2018 to 2025). "In rats with thermal injury and endotoxemia, treatment with IGF-1/IGFBP-3 improved villous height and cell count per villus by reducing epithelial apoptosis and promoting proliferation." (PMID 40724799, 2025).
esophageal tumor (2 papers, 2012 to 2021). "IGFBP3 plays a key role in esophageal tumor progression and metastasis by facilitating EMT." (PMID 34944855, 2021).
gastric adenocarcinoma (2 papers, 2013 to 2015). "Our findings were consistent with previous report that well or moderate-differentiated gastric adenocarcinomas had significantly higher percentage of IGFBP3 staining in tumor tissues than those in poor-differentiated ones." (PMID 24386080, 2013). "Immunohistochemical staining results revealed that IGFBP3 expression was significantly downregulated in 86 gastric adenocarcinomas tissues relative to their adjacent non-cancerous tissues (p<0.001)." (PMID 24386080, 2013). "In addition, down-regulation of IGFBP-3 in 86 gastric adenocarcinoma tissues relative to their adjacent non-cancerous tissues by immunohistochemistry was reported, and patients with high expression of IGFBP-3 showed a higher 5-year OS rate." (PMID 26370590, 2015).
gastrointestinal stromal tumor (2 papers, 2009 to 2022). "In contrast to many studies in which IGFBP-3 is tumor-suppressive, IGFBP-3 seems to act as an oncogene in gastrointestinal stromal tumors (GIST), in which low expression of miR-186 is proposed to increase metastasis through the upregulation of IGFBP-3 and several other metastatic genes." (PMID 35597813, 2022).
HELLP syndrome (2 papers, 2023 to 2025). A life-threatening condition that can potentially complicate pregnancy. "Correlation analysis was used to observe the correlation between IGFBP-3 and IGF-1/TGF-β1/VEGF in maternal and umbilical blood, as well as that between maternal serum IGFBP-3 and clinical diagnostic indicators of HELLP syndrome." (PMID 37950229, 2023). "However, our study only preliminary verified the association between IGFBP-3 and HELLP syndrome, being certain limitations." (PMID 37950229, 2023). "This suggests that IGFBP-3 may be associated with the abnormal degree of diagnostic indicators of HELLP syndrome, and also somewhat reflects the severity of the disease, which causes concern among clinicians." (PMID 37950229, 2023). "Recent findings suggest that IGFBP-3 levels are significantly elevated in maternal serum in HELLP syndrome compared to normal pregnancies, supporting its potential role in the pathophysiology of this condition." (PMID 41333061, 2025). "Through experimental verification in clinical specimens and cells, we carried out research on the expression of IGFBP-3 in HELLP syndrome and its clinical significance in this study." (PMID 37950229, 2023). "It confirmed our deduction that IGFBP-3 acts on HELLP syndrome by affecting the VEGF/eNOS/NO pathway." (PMID 37950229, 2023). "In summary, this study was the first to investigate the correlation between IGFBP-3 and HELLP syndrome." (PMID 37950229, 2023). "Firstly, we have only demonstrated elevated IGFBP-3 level in clinical specimens from patients who have already developed HELLP syndrome." (PMID 37950229, 2023). "By ELISA, we found that the level of IGFBP-3 in maternal and umbilical blood of HELLP syndrome patients was higher than in normal healthy pregnant women and PE patients, which was consistent with our previous results from protein microarray analysis." (PMID 37950229, 2023). "Thus, an increased level of IGFBP-3 likely plays a role in HELLP syndrome by promoting apoptosis and impairing liver and endothelial function." (PMID 41333061, 2025). "The expression of IGFBP-3 is elevated in HELLP syndrome, which may subsequently promote cell apoptosis by affecting the expression and function of IGF-1, VEGF, and TGFβ1 in the IGF/PI3K/Akt, TGF-β1/Smad3, and VEGF/eNOS/NO pathways." (PMID 37950229, 2023). "Therefore, it can be inferred that IGFBP-3 is involved in the pathophysiology of HELLP syndrome by increasing apoptosis and affecting the normal function of the liver and vascular endothelium." (PMID 37950229, 2023). "We determined that IGFBP-3 expression was significantly higher in patients with HELLP syndrome, which may play a crucial role in the pathophysiological changes of this disease." (PMID 37950229, 2023). "However, it is impossible to study all the differential proteins at the same time, so we focused on IGFBP-3 at first, and will explore its interaction with other differential proteins in the pathophysiological changes of HELLP syndrome after achieving phased results in future." (PMID 37950229, 2023). "Moreover, the moderate inverse correlation between maternal VEGF levels and IGFBP-3 was consistent with the hypothesis that IGFBP-3 plays a role in HELLP syndrome by inhibiting VEGF." (PMID 37950229, 2023). "Consequently, the level of IGFBP-3 in HELLP syndrome patients is higher than in PE patients." (PMID 37950229, 2023). "Hence, those pregnant women with elevated serum IGFBP-3 before diagnosed as HELLP syndrome, especially PE patients, whether or not their risk of developing HELLP syndrome will be correspondingly higher?" (PMID 37950229, 2023). "Through bioinformatics analysis, we gradually focused on IGFBP-3, which had not been reported in the field of HELLP syndrome." (PMID 37950229, 2023). "To date, IGFBP-3 has not yet been studied in HELLP syndrome." (PMID 37950229, 2023). "Therefore, IGFBP-3 may be important in the pathological mechanism of HELLP syndrome, but it does not necessarily play an effect alone." (PMID 37950229, 2023).
hip fracture (2 papers, 2024 to 2025). Traumatic or pathological injury to the hip in which the continuity of either the femoral head, femoral neck, intertrochanteric or subtrochanteric regions is broken. "The authors reported that sarcopenic hip fracture patients had significantly lower serum albumin, IGF-I, insulin-like growth factor binding protein 3 (IGFBP-3), and free testosterone levels, as well as impaired beta cell function according to homeostasis model assessment (HOMA beta)." (PMID 39769198, 2024).
hip osteoarthritis (2 papers, 2016 to 2018). "On the other hand, genome‐wide association and functional studies have shown that IGFBP3 overexpression induced cartilage catabolism and osteogenic differentiation in hip osteoarthritis." (PMID 29219174, 2018).
IgA nephropathy (2 papers, 2021 to 2024). "In primary nephropathy, IGFBP-3 is involved in the development of IgA nephropathy and podocytosis." (PMID 35002740, 2021). "IGFBP-3 was found to be up-regulated in the kidney of experimental IgA nephropathy." (PMID 35002740, 2021).
inflammatory bowel disease (2 papers, 2020 to 2025). A spectrum of small and large bowel inflammatory diseases of unknown etiology. "In accordance with our results, previous studies found endogenous IGF-1 and IGFBP-3 levels negatively associated with the degree of inflammation both in HSCT settings and in patients with inflammatory bowel disease." (PMID 32793242, 2020). "The IGF-1/IGFBP-3 complex has been shown to exert anti-apoptotic effects on small intestinal epithelial cells, and lower IGFBP-3 levels have been associated with disease activity in inflammatory bowel disease." (PMID 40724799, 2025).
insulinoma (2 papers, 2015 to 2024). "A low expression of both TMEM219 mRNA and protein and a high mRNA expression of MKI67, were evident in the insulinoma samples, with circulating levels of the TMEM219 ligand IGFBP3 also being reduced, thus suggesting a dysregulation of the TMEM219 signaling." (PMID 38318298, 2024).
islet cell tumor (2 papers, 2006 to 2016). "In patients with non-islet cell tumor the pool of big-IGF2 increases and 80 % of this molecule is bounded to IGFBP3 only, forming a lower molecular weight that crosses the endothelial barrier and acts on insulin receptors." (PMID 27134683, 2016).
Laron syndrome (2 papers, 2018 to 2022). Laron syndrome is a congenital disorder characterized by marked short stature associated with normal or high serum growth hormone (GH) and low serum insulin-like growth factor-1 (IGF-I) levels which fail to rise after exogenous GH administration. "This is significantly different from injections of rhIGF1 in human Laron syndrome with absence of GH dependent IGFBP3 and ALS after treatment." (PMID 35105948, 2022).
lymphocytopenia (2 papers, 2022 to 2025). "In our cohort, patients with IGFBP-3 levels below 10.64 exhibited significantly lower median lymphocyte counts and a higher prevalence of severe lymphocytopenia at baseline compared to those with higher IGFBP-3 levels." (PMID 40724799, 2025). "Furthermore, our findings show that lower IGFBP-3 levels are associated with elevated IL-6 concentrations and more severe lymphocytopenia, suggesting a possible synergistic role of IGFBP-3 and IL-6 in exacerbating immune suppression." (PMID 40724799, 2025).
mesothelioma (2 papers, 2020 to 2024). A usually malignant and aggressive neoplasm of the mesothelium which is often associated with exposure to asbestos. "Similar results were observed for clinical subgroups in mesothelioma, the pan-kidney cohort, rectum adenocarcinoma, colorectal adenocarcinoma, and colon adenocarcinoma cancers, where low expression of IGFBP-3 was similarly associated with better survival outcome." (PMID 32443727, 2020). "However, the elevation of IGFBP-3 secretion was not altered in non-epithelioid CRL-5946 cells, implying potential differences in the FK228 response between the two mesothelioma cell types." (PMID 38822233, 2024).
metastatic carcinoma (2 papers, 2004 to 2024). A carcinoma which has spread from the original site of growth to another anatomic site. "IGFBP3 expression was similar in HGPIN, invasive carcinoma, and metastatic carcinoma." (PMID 15318950, 2004).
migraine (2 papers, 2021 to 2022). "The KH patient with a heterozygous NEK11 mutation had recurrent migraine, cognitive and motor deficits, mild liver affection, absent glucose response to i.m. glucagon and decreased p-IGFBP3 as additional features." (PMID 33849624, 2021).
narcolepsy (2 papers, 2009 to 2020). A sleep disorder characterized by a tendency for excessive sleepiness during the day which occurs even after adequate sleep in the nighttime. "Further studies are required to address the hypothesis that excessive IGFBP3 expression may initiate hypocretin cell death and cause narcolepsy." (PMID 19158946, 2009). "We investigated whether human narcolepsy is associated with dysregulated IGFBP3 levels in the blood and CSF." (PMID 19158946, 2009). "Other transcripts were also found, only one of which, IGFBP3, was downregulated in human narcolepsy hypothalami." (PMID 19158946, 2009). "IGFBP3 levels were similar in CSF and serum of narcolepsy versus controls, and it is abundant in various human brain cells, possibly reflecting cellular uptake of circulating IGFBP3." (PMID 19158946, 2009). "Mean levels of IGFBP3 in age and sex matched narcolepsy patients (all with low CSF hypocretin-1) versus controls were 59.4±3.4 ng/ml (n = 11) and 58.0±4.5 (n = 11) ng/ml in serum and 31.2±2.1 ng/ml (n = 27) and 29.0±1.9 ng/ml (n = 35) in CSF respectively." (PMID 19158946, 2009). "Although we found no IGFBP3 autoantibodies nor a genetic association with IGFBP3 polymorphisms in human narcolepsy, we found that an IGFBP3 polymorphism known to increase serum IGFBP3 levels was associated with lower CSF hypocretin-1 in normal individuals." (PMID 19158946, 2009). "Even if not directly involved as an autoantigen in causing narcolepsy, IGFBP3 is still an interesting candidate as it plays key roles in regulating cell proliferation and apoptosis." (PMID 19158946, 2009). "The results above do not support the involvement of IGFBP3 in causing hypocretin cell death in narcolepsy." (PMID 19158946, 2009). "What function could IGFBP3 have in hypocretin producing cells with regard to narcolepsy?" (PMID 19158946, 2009). "Functional analysis indicated that the identified IGFBP3 is a new regulator of hypocretin cell physiology that may be involved not only in the pathophysiology of narcolepsy, but also in the regulation of sleep in normal individuals, most notably during adolescence." (PMID 19158946, 2009).
nutritional rickets (2 papers, 2010 to 2019). "The increase in both IGF-I and IGFBP-3 levels after the treatment of rickets may be due to a direct stimulatory effect of vitamin D and/or to improvement of nutritional status." (PMID 21274331, 2010). "Serum IGF-I and IGFBP-3 levels both increased after treatment for rickets, while serum IGFBP-4 levels did not change significantly (18.8±8.0 vs. 21.5±4.8 ng/ml)." (PMID 21274331, 2010). "Thus, to investigate the role of PTH in the regulation of IGFBP-4 levels, we prospectively measured serum IGF-I, IGFBP-3, IGFBP-4 and PTH concentrations in infants with nutritional rickets before and after treatment." (PMID 21274331, 2010). "In a study of children with nutritional rickets, vitamin D supplementation increased serum IGF-I and IGFBP-3 and resulted in accelerated linear growth, suggesting that the treatment of poor growth associated with rickets might be mediated through activation of the IGF axis." (PMID 31071681, 2019).
ovarian tumors (2 papers, 2017 to 2025). "For example, IGFBP-2 induction has been shown to activate cell invasion, and increased levels of IGFBP-2 have been reported in ovarian tumour tissues and serum, as well as increased IGFBP-3 mRNA expression in HNSCC compared to healthy tissue." (PMID 28143425, 2017). "Insulin-like growth factor-1 (IGF-1), insulin-like growth factor binding protein-3 (IGFBP-3), leptin, the HOMA (hemostasis model assessment) score, fasting glucose, and calcium-125 can be used to differentiate between ovarian tumors and benign ovarian lesions." (PMID 41303820, 2025).
pancreatic adenocarcinoma (2 papers, 2010 to 2016). "Numerous genes were overexpressed, some of which have previously been implicated in pancreatic adenocarcinoma (GATA6, IGFBP3, IGFBP6), while others were detected for the first time (MEMO1, RIOK3)." (PMID 20553613, 2010).
pancreatic endocrine neoplasms (2 papers, 2015 to 2022). "High expression of IGFBP3 (insulin‐like growth factor binding protein 3) has been associated with lymph node and liver metastasis, and poor outcome in CRC and pancreatic endocrine neoplasms." (PMID 36134447, 2022).